NES (nestin)
Diseases named in the same sentence as NES in open-access papers (continued):
Sharing a sentence is not in itself a finding about the gene and the disease.
cancer (continued). "Weak nestin expression was correlated with favorable characteristics of cancer, decreased incidence of local recurrence and lower risk of recurrence within 12 months after surgery." (PMID 25371063, 2015). "Overall, positive/high nestin was significantly associated with median or advanced stages of several types of cancer (nestin and cancer stage: OR = 1.90, 95% CI = 1.30–2.78; nestin and lymph node: OR = 2.17, 95% CI = 1.26–3.72)." (PMID 26015397, 2015). "Overall, there was evidence for an association between positive/high nestin and median/advanced cancer stage in different cancers when all eligible studies were pooled into the meta-analysis." (PMID 26015397, 2015). "Univariable analysis indicated that nestin expression, lymphovascular invasion, and lymph node status were significantly associated with cancer-specific survival (hazard ratios, 2.78, 2.15, and 2.80, respectively)." (PMID 24785714, 2014). "The association between nestin expression and clinical outcomes in patients with cancer is gradually being clarified." (PMID 24785714, 2014). "The association of nestin expression with the rate of progression-free survival and cancer-specific survival and overall survival were analyzed using Kaplan–Meier analysis." (PMID 24785714, 2014). "Cancers that express the basal CK-5 or the cell stemness-linked proteins prominin-1 or nestin are associated with the brain as the first site of distant recurrence." (PMID 21914172, 2011). "Notably, nestin deficiency has been shown to reverse drug resistance, highlighting its potential as a therapeutic target to enhance the efficacy of cancer treatment." (PMID 40799240, 2025). "Because nestin gets phosphorylated at Thr-315 in cancer cells and is associated with cell proliferation, we questioned whether contractile stimulation affects nestin phosphorylation at this position." (PMID 37316833, 2023). "Intermediate filaments vimentin and nestin are associated with different types of cancer." (PMID 33919917, 2021). "Nestin is reportedly linked to chemoresistance through EMT in various cancers, including NSCLC." (PMID 32903755, 2020). "And Nestin was associated with cancer stage, lymph node, and poor outcome." (PMID 27150062, 2016). "For example, positive/high nestin may be more strongly linked to advanced cancer stage and correlated with malignant characteristics that lead to poor prognosis in different cancers, especially lung cancer." (PMID 26575328, 2016). "Nestin is expressed in several types of cancer and it is strongly associated with GBM." (PMID 27148537, 2016). "And the authors found that Nestin was positively associated with cancer stage and lymph node." (PMID 27150062, 2016). "Moreover, Nestin is also expressed in malignant tumor cells and is associated with tumor cell proliferation and metastasis in colorectal, breast, prostate, and pancreatic cancers." (PMID 27894083, 2016). "Because of the relatively small sample sizes and limited statistical power of these individual, inconclusive studies, it is important to summarize the results from different studies to more accurately assess the association of positive/high nestin with cancer stage." (PMID 26015397, 2015). "However, this study demonstrated that positive nestin expression is associated with poor prognosis and is an independent prognostic factor for cancer-specific survival in patients with UCB after radical cystectomy." (PMID 24785714, 2014). "Besides, the subgroup analysis also suggested that differences in cancer type may significantly affect the association between nestin expression and OS." (PMID 37485559, 2023). "Nestin might be involved in tissue homeostasis or repair, but its expression has also been associated with processes that lead to a poor prognosis in various types of cancer." (PMID 34943921, 2021). "We hypothesize that nestin modulates cancer progression and is associated with patient survival." (PMID 25371063, 2015).
cancer (continued). "Recent reports have indicated that nestin might be linked to malignant characteristics, suggesting that abundant nestin expression correlates with greater malignancy and poorer prognosis in different cancers." (PMID 26015397, 2015). "This is in line with the current knowledge of Nestin being a key player in proliferation capability in different cancer entities, e.g. PDAC." (PMID 41129070, 2026). "Hh signaling induces the upregulation of Gli1, promoting the expression of nestin in both cancer stem cells and neural progenitor cells." (PMID 40799240, 2025). "After CA treatment, the mRNA expression of the cancer stem cell-related genes Nestin, OCT4, and CD133 in GBM8401-CSC was significantly reduced, further supporting the ability of CA to inhibit stem cell characteristics." (PMID 41209573, 2025). "Recently, nestin has been reported to be a useful marker and therapeutic target of cancer stem cell (CSC) in solid tumors, reflecting its importance in drug resistance and poor prognosis." (PMID 40799240, 2025). "After culturing in stem cell medium, the expression of cancer stem cell markers such as Nanog, Sox2, Nestin, and oligodendrocyte transcription factor 2 (Olig2) in GSC spheres was confirmed by immunostaining." (PMID 39721005, 2025). "GBM8401-CSC formed more neurospheres, had stronger colony-forming ability, and showed higher mRNA expression of cancer stemness factors than did GBM8401 cells (Nestin, OCT4, CD133)." (PMID 41209573, 2025). "Introducing RCAS vectors expressing SHh and c-Myc into nestin+ progenitor cells can induce proliferation and transformation into malignant tumor cells, leading to tumorigenesis." (PMID 40799240, 2025). "In MM, it is manifested as excessive production of ROS, and nestin has been found to promote cancer cell antioxidant activity, thereby promoting proliferation, invasion, and drug resistance." (PMID 40799240, 2025). "A high content of Nestin, the protein encoded by the NES gene, is a feature of MB CSCs and SHH-driven cancers." (PMID 39851500, 2025). "In this study, we founded that GBM8401-derived cancer stem cells (GBM8401-CSCs) display increased stemness, proliferation, migration, invasion, and elevated cancer stemness factors (Nestin, OCT4, CD133) compared to parental cells." (PMID 41209573, 2025). "An increasing number of studies suggest that nestin is involved in the regulation of proliferation, invasion, and drug resistance in various cancers." (PMID 40799240, 2025). "Based on these studies, inhibiting nestin can help suppress stemness, leading to reduced proliferation, invasion, and drug resistance of cancer cells." (PMID 40799240, 2025). "In contrast, levels of several epithelial‐mesenchymal transition (EMT)‐ and cancer stem cell (CSC)‐related markers including Nestin, ALDH1, ZEB1, Slug, and Twist 1 were lower in OE‐ALKATI cells when compared to mock cells." (PMID 40387841, 2025). "NES, frequently overexpressed in cancer cells, correlates with poor prognosis and cisplatin resistance, indicating its role in acquired drug resistance." (PMID 39401197, 2024). "Next, we further explored the expression of the cancer stem cell markers Notch1, Nestin, and CD133 in GBM." (PMID 38473403, 2024). "The growth was driven by Nestin and Ki67 double-positive cells in a putative cancer stem cell niche, which was manifested as rosette-looking clusters in 2D and spheroids in 3D." (PMID 37508868, 2023). "Overall, 2453 patients with DTCs were included in this meta-analysis, and 884 (36%) of them were with higher expression of nestin in cancer tissue." (PMID 37485559, 2023). "These predictions attracted our attention because nestin has been reported to be involved in 1) the regulation of migratory and invasive phenotypes of cancer cells and 2) the cytoskeletal re-organization in different cell subsets." (PMID 38008717, 2023).
cancer (continued). "Our study revealed that BTICs not only express cancer stem cell markers Nestin and CD133,32, 33, 34, 35 they can also differentiate into multiple neural lineages." (PMID 36321378, 2023). "We used flow cytometry to quantify different cell types in cultures, including neural, stem/progenitor cells (Nestin), cancer stem cells (CD133) neuronal (TUJ1), glial (GFAP), and the proliferative population (Ki67)." (PMID 37508868, 2023). "In conclusion, According to this meta-analysis, higher nestin expression in cancer tissue predicts poor survival in patients with DTCs, particularly in those with GC and LC patients." (PMID 37485559, 2023). "In our 2D cultures, similar rosette-looking patterns emerged from confluent monolayers; Nestin and Ki67 double-positivity suggested a cancer stem cell-enriched growth niche." (PMID 37508868, 2023). "For example, promotors of cancer stem-cell-expressed genes such as Nestin and Musashi-1 have been exploited to drive ICP34.5 expression to increase virus replication in cancer cells, but not in normal adult cells where these promotors are not active." (PMID 35062322, 2022). "To extend the cellular effect of NDG1 to molecular presentations, we determined the expression of cancer stemness-associated regulators (ABCG2, Twist1, BMI1, NES, c-Met) in NDRG1-FL-transfected HNC cells." (PMID 35563887, 2022). "Nestin is a class VI intermediate filament protein that is involved in the proliferation/regeneration of neurons, cancer cells, and skeletal muscle." (PMID 36231009, 2022). "CCL2, CRIM1, COL1A1, 6A1, 6A2 participate in cell migration, invasion, or EMT and ABCG2, ALDH1A1, NES are cancer stem‐cell markers." (PMID 36305167, 2022). "We found that DHEA reduced HNSCC cell viability, suppressed sphere formation, and inhibited the expression of cancer-stemness markers, such as BMI-1 and Nestin." (PMID 35912234, 2022). "Nestin is involved in the proliferation of neurons and cancer cells and the regeneration of skeletal muscle." (PMID 36231009, 2022). "Subsequently, nestin was found in cancer cells, including lung adenocarcinoma and regenerative skeletal muscle." (PMID 36231009, 2022). "The role of nestin in cancer cell migration is complex, as its effects vary depending on cell types." (PMID 36231009, 2022). "Expression of the prominent CSC markers CD133, CD44, and Nestin as well as successful formation of spherical cancer organoids confirmed a CSC-like phenotype." (PMID 33925297, 2021). "Several studies suggested that Nestin expression is directly proportional to the activity and properties of cancer stem cells in different tumors with high expression, cor relating to poor prognosis." (PMID 33584136, 2021). "Nestin is a common marker of multipotent stem cells, and its expression is significantly upregulated in tissue injury and cancer progression." (PMID 34772403, 2021). "Nestin is a neural stem cell protein that plays an important role in cancer stem cells (CSC) development and proliferation." (PMID 33584136, 2021). "On the other hand, several studies have reported that nestin is a marker of cancer stem cells (CSCs) expressed in malignancies of organs such as the brain, uterus, cervix, prostate, ovary, testis, and pancreas." (PMID 34943921, 2021). "Intermediary filament (keratins, vimentin and nestin) have been postulated to act as tumoral and metastasis development effectors, following the “hallmarks of cancer” described by Hanahan and Weinberg, keeping cell stemness through CDK5 inhibition." (PMID 33805026, 2021). "A phenotypical characterisation of the migrated subpopulations revealed that the majority of them were nestin and fibroblast growth factor receptor 1 positive, an indication of their cancer stem cell origin." (PMID 33637089, 2021).
cancer (continued). "Nestin is a common marker of multipotent stem cells that, according to extensive reports, is dysregulated by tissue injuries and cancer progression." (PMID 34837964, 2021). "Nestin is a neural stem cell protein that plays an important role in cancer stem cells (CSC) development and multiplication." (PMID 33584136, 2021). "Nestin has been shown to function as a survival factor to inhibit CDK-5 dependent apoptosis, whilst the knockdown of nestin in cancer cells was reported to reduce cell motility." (PMID 31963677, 2020). "In recent years, some reports showed that besides neural stem cells, other cells like mesenchymal like cells and even cancer cells also expressed Nestin." (PMID 33391003, 2020). "Our results showed a homogenous expression of Vimentin in all primary cancer cell lines, whereas a differential expression pattern of Nestin was noted." (PMID 32742192, 2020). "GFP-tagged Nestin protein of several cancer cell lines including CRC revealed a high GFP expression in proliferating endothelial cells and nascent blood vessels in the growing tumors." (PMID 33260962, 2020). "Nestin, a type VI intermediate filament, is often re-expressed in cancer cells, including gliomas, osteosarcoma, colorectal and prostate cancers." (PMID 31963677, 2020). "Findings since then have provided support for the role of nestin as a critical element in stemness of cancer cells." (PMID 31126068, 2019). "For many years, select IF proteins, most notably nestin, have been used as markers of cancer stem cells in various cancer types." (PMID 31126068, 2019). "The role of nestin on tumorigenesis and stemness of cancer cells has previously been reviewed by others." (PMID 31126068, 2019). "In cancer, nestin has been found to be expressed in cancer stem-like cells and poorly differentiated cancer cells." (PMID 31126068, 2019). "This is particularly true for those IF proteins, such as nestin, that are critical for cancer stem cell maintenance, as cancer stem cells play key roles in resistance to conventional chemotherapy." (PMID 31126068, 2019). "Nestin is commonly used as a marker for neural stem cell and cancer stem cell populations, and its expression increases progressively during MB development." (PMID 31297057, 2019). "Many studies have evaluated the implication of nestin in human cancers and proved it to be a reliable biomarker." (PMID 31675305, 2019). "Our method can not only prioritize the significant cancer driver genes but also identify some potential cancer driver genes which were neglected by the NCG 4.0 such as the NES, MET and HGF." (PMID 31888619, 2019). "In this review, we will discuss the functions of IF proteins in cancer, focusing on a subset of IFs that have been most widely studied in the context of cancer—keratins, vimentin, and nestin." (PMID 31126068, 2019). "Nestin is an IF protein whose expression is upregulated in numerous cancers, and is correlated with aggressive behavior and poor prognosis." (PMID 30190500, 2018). "Focusing on the presence of pluripotency markers thereafter, we observed increased gene expression of Krüppel-like factor 4 (Klf4) and N-myc, while Nestin, a putative marker of cancer stem cells, decreased." (PMID 30185144, 2018). "Nestin can be localised in the nucleus of cancer cells, but its nuclear role in tumorigenesis is unclear." (PMID 30190500, 2018). "To further investigate the molecular mechanism responsible for the disassembly of lamin A/C in Nestin-knockdown cancer cells, we treated Nestin-knockdown and control cells with inhibitors of Cdk1/2/5 and Akt, respectively." (PMID 30190500, 2018). "GSEA revealed that genes associated with cancer stem cells (CSC) (e.g., NES, TSPAN8, DPPP, DNAJC12, and MYC) were highly ranked and comprised 70% of the top 25 genes differentially upregulated in the DTX-resistant cells." (PMID 30100995, 2018). "Using immunocytochemistry, we showed the expression of cancer stem cell markers Nestin and SOX on BTICs." (PMID 30200299, 2018).
cancer (continued). "Nestin is an extensively studied marker of neural stem cells that is a putative marker of the cancer stem cell (CSC) phenotype, as its expression has been identified in many human malignancies." (PMID 28358810, 2017). "Nestin is a class VI intermediate filament protein expressed in neural stem cells and several cancer cells including NSCLC." (PMID 28358810, 2017). "As expected, the phosphorylated states of STAT3 were markedly inhibited by WP1066 and S3 l-201, so as the cancer stem cell markers Nestin, SSES-1, and NANOG." (PMID 29284440, 2017). "Recent observations have revealed a link between Nestin aberrant expression and malignant characteristics and poor prognosis in different cancers." (PMID 27150062, 2016). "A number of studies have been performed to explore the associations of cancer cell stem cell markers, such as SOX2 and Nestin, with clinical parameters and prognosis in various types of cancers including NSCLC." (PMID 27150062, 2016). "Not only were EphA3 protein levels increased in tumorspheres, we also observed a high degree of co-staining with the cancer stem cell marker Nestin in situ." (PMID 27494882, 2016). "Given our finding that high levels of Nestin expression induce EMT, there is a high likelihood that Nestin+/CD44v8-10+ cells correspond to those cancer stem cells that give rise to relapse, metastasis and chemo-resistance." (PMID 27412382, 2016). "Challenge of PANC-1 cells with GEM increased the expression of stemness markers including CD133, nestin and Lgr5 and promoted sphere forming activity suggesting chemotherapy enriched cancer cells with stem-like properties." (PMID 27531902, 2016). "Given that proliferation and self-renewal are features shared by progenitor/stem cells and cancer cells, the up-regulation of Nestin in both cell types suggests that Nestin is involved in the proliferation and growth of NPCs." (PMID 27894083, 2016). "Patients with mild to strong nestin expression exhibited an advanced behavior of cancer and increased possibility of cancer recurrence." (PMID 25371063, 2015). "Seven articles that included a total of 223 cases and 460 controls were used to evaluate the relationship between nestin with cancer stage." (PMID 26015397, 2015). "Ultimately, additional large scale-studies with more detailed individual data are warranted to further validate the relationship of nestin with cancer stage." (PMID 26015397, 2015). "The level of nestin mRNA expression was detected in the 15 pairs of cancer and normal tissue samples." (PMID 25371063, 2015). "Patients with nestin expression in cancer cells had varied prognosis: those with weak nestin expression had a favorable recurrence-free survival, whereas those with mild to strong nestin expression had an unfavorable survival." (PMID 25371063, 2015). "On multivariable analysis, nestin expression and lymph node status were independent prognostic factors in cancer-specific survival (hazard ratios, 2.45 and 2.65, respectively)." (PMID 24785714, 2014). "Nestin status was correlated with poorly differentiated phenotype (χ2 = 17.776, P = 0.006), histological cancer tissue type (χ2 = 8.215, P = 0.002), N classification (χ2 = 12.093, P = 0.001), and vital status (χ2 = 9.003, P = 0.003)." (PMID 24498263, 2014). "Univariable and multivariable analyses for the effect of nestin expression on recurrence and cancer-specific survival." (PMID 24785714, 2014). "Recent reports support a link between nestin and malignant characteristics, and suggest that abundant nestin expression is correlated with greater malignancy and poorer prognosis in different cancers." (PMID 24498263, 2014). "Recent reports have linked nestin with malignant characteristics in different cancers and suggested that abundant nestin positive cancer cells correlate with greater malignancy and poor prognosis." (PMID 24966803, 2014). "Our differentiation assays suggests that Oct4 cells give rise to cancer cells expressing nestin and NeuN." (PMID 24160469, 2013).